GAS5 (growth arrest specific 5)
Diseases named in the same sentence as GAS5 in open-access papers (continued):
Sharing a sentence is not in itself a finding about the gene and the disease.
gastric cancer (continued). "The lncRNA growth-arrest-specific transcript 5 (GAS5) is suppressed in diverse cancers, such as ovarian cancer, cervical cancer and gastric cancer, indicating that GAS5 may play a tumor-suppressive role." (PMID 38540273, 2024). "GAS5:39 and lnc-MB21D1-3:5 were high expressed in the identified gastric cancer tissues than NCs." (PMID 34295803, 2021). "For example, the predicted global score for GAS5 and gastric cancer ranks 6th out of all the 60,169 non-zero predicted results by FRMCLDA." (PMID 31572428, 2019). "In this study, we found that lncRNA GAS5 had lower expression in stomach cancer tissues than the normal counterparts." (PMID 25959498, 2015). "Similar in another study, GAS5 promoted the secretion of IFN-γ and TNF-α by regulating miR-18a, thereby enhancing the killing effect of NK cells on gastric cancer (GC)." (PMID 35222443, 2022). "However, the roles of GAS5 and the mechanisms responsible for its functions in gastric cancer (GC) have not been well documented." (PMID 31182630, 2019). "However, the mRNA expression of E2F1, cyclinD1 or P21 remained unaltered in the GAS5-overexpressed gastric cancer cells compared with the vector controls (data not shown)." (PMID 24884417, 2014). "In contrast to the previous observation that lncRNA GAS5 decreases CDK6 mRNA and protein levels in bladder cancer, our results indicate that lncRNA GAS5 knockdown reduced the YBX1 protein level without affecting its transcription in stomach cancer." (PMID 25959498, 2015).
prostate carcinoma (62 papers, 2013 to 2025). A carcinoma that arises from epithelial cells of the prostate gland. "The primary objective of this study was to evaluate the relationship between circulating Humanin levels, Long Non-Coding RNA GAS5, microRNA-21 (miR-21), microRNA-103 (miR-103), and prostate cancer risk." (PMID 40768089, 2025). "The rs17359906 in GAS5 is another SNP whose A allele has been shown to be a risk allele for prostate cancer." (PMID 37025585, 2023). "Carriers of the Ins/Del or Del/Del genotype of GAS5 rs145204276 are at low risk for pathological lymph node metastasis of prostate cancer in Taiwanese populations." (PMID 32354045, 2020). "This is the first study to report the correlation between GAS5 gene polymorphism and prostate cancer prognosis." (PMID 31673232, 2019). "But, there are only 158 PCa patients included in this study, and this sample size is a little below power to conclude the susceptibility of prostate cancer and SNP of GAS5." (PMID 31673232, 2019). "We aimed to investigate the effect of variant rs145204276 of GAS5 on the prostate cancer susceptibility and clinicopathologic characteristics." (PMID 31673232, 2019). "In a separate study relating to prostate cancer, increased expression of GAS5 was associated with decreased Akt signalling." (PMID 29701689, 2018). "In a previous study, we identified that patients with prostate cancer and the Ins/Del or Del/Del genotype of GAS5 rs145204276 were at a significantly decreased risk of pathological lymph node metastasis compared with those with the Ins/Ins genotype (odds ratio (OR) = 0.545; p = 0.043)." (PMID 32354045, 2020). "We detected PCA3, PVT1, and GAS5 lincRNAs as differentially expressed genes in the patient cancer samples compared with adjacent non-tumor tissues; these lincRNAs have been recently shown to be associated with prostate cancer." (PMID 29875794, 2018). "Down regulation of the lncRNA GAS5 is associated with a poor prognosis in prostate cancer." (PMID 28993733, 2017). "Interestingly, one current clinical trial is aimed at further identifying and validating the role of GAS5 in prostate cancer through the detection and characterization of GAS5 gene polymorphisms (clinicaltrials.gov; accessed on 29 January 2025 ID: NCT06505356)." (PMID 39941145, 2025). "Thus, the effect of GAS5 SNP about prostate cancer susceptibility became attenuated." (PMID 31673232, 2019). "This study advances our understanding of the molecular roles of mitochondrial-derived peptides Humanin and MOTS, the long non-coding RNA GAS5, and the oncogenic microRNAs miR-21 and miR-103 in prostate cancer." (PMID 40768089, 2025). "In prostate cancer, GAS5 functions by inducing apoptosis and repressing androgen receptor (AR) activity, sequestering the androgen/AR complex and inhibiting the AR signaling pathway, which is vital for prostate cancer cell survival and growth." (PMID 40242248, 2025). "In our study, GAS5 expression—especially in plasma—was significantly reduced in prostate cancer, reinforcing its proposed tumor-suppressor role." (PMID 40768089, 2025). "Dexamethasone can up-regulate lncRNA GAS5 expression in prostate cancer, whereas it down-regulated GAS5 expression in diabetes." (PMID 37953323, 2024). "This phenomenon is not restricted to the AR-negative subtype, as GR can induce FOXO3 and GAS5 expression in AR-positive prostate cancer cells as well." (PMID 39027480, 2024). "Contribution of single nucleotide polymorphisms (SNPs) within GAS5, POLR2E, MEG3, MALAT1 and HOTAIR in the risk of prostate cancer has been assessed in different ethnic groups." (PMID 37025585, 2023). "Similar findings in prostate cancer cells showed that high GAS5 levels increase both basal and drug-induced apoptosis, whereas downregulation of GAS5 attenuates apoptosis." (PMID 35736636, 2022).
prostate carcinoma (continued). "For instance, lncRNA GAS5 is a tumor-suppressor factor in prostate cancer and its overexpression decreases miRNA-103 to inhibit Akt/mTOR signaling, leading to a significant decrease in proliferation and metastasis." (PMID 35773731, 2022). "In this case, siRNA application diminishes GAS5 expression in increasing prostate cancer progression, revealing anti-tumor activity of GAS5." (PMID 35773731, 2022). "Studies had also shown that GAS5 rs145204276 and HOTAIR rs4759314 polymorphisms affected the expression of GAS5 and HOTAIR, affecting the survival rates of prostate cancer." (PMID 33391419, 2021). "First of all, instead of the measured docetaxel response in prostate cancer patients, we utilized the docetaxel sensitivity score imputed using patients’ RNAseq data to perform the correlation between GAS5 expression and docetaxel response." (PMID 34094978, 2021). "For example, GAS5-007, which is one of the transcripts of GAS5, promotes cell proliferation and inhibits cell apoptosis of prostate cancer." (PMID 33391419, 2021). "GAS5 silencing induces resistance to, and ectopic GAS5 expression confers sensitivity to, the cytostatic effects of mTOR inhibitors, thereby demonstrating a role for GAS5 lncRNA in mTOR inhibitor action in prostate cancer." (PMID 31533355, 2019). "Pickard and his colleagues have presented abnormally low levels of GAS5 expression in prostate cancer cells and GAS5 upregulation boosts apoptosis and reduces 22Rv1 cell survival." (PMID 31182630, 2019). "GAS5 expression is significantly decreased in prostate cancer cells compared with prostate epithelial cells." (PMID 30853980, 2019). "The transcript levels of lncRNA growth-arrest specific 5 (GAS5) can be enhanced by mTOR inhibition in certain prostate cancer cell lines." (PMID 30671083, 2018). "Of further interest, GAS5 lncRNA has been found to supress the AKT/mTOR signaling pathway in prostate cancer cells." (PMID 30087896, 2018). "To explore the molecular mechanisms involved in different transcripts of GAS5 regulating prostate cancer progression, we selected other two transcripts (GAS5-002 and GAS5-001) and constructed lncRNA-miRNA networks based on bioinformatic analysis in this study." (PMID 28771526, 2017). "In prostate cancer, there have been studies demonstrated that two transcripts of GAS5 (GAS5-O1 and GAS5-AE) promoted the apoptosis of prostate cancer cells." (PMID 28771526, 2017). "In our study, investigated the exosomal GAS5 and lincRNA-p21 lncRNA levels in urine samples from 30 patients with prostate cancer (PCa) and 49 patients with benign prostatic hyperplasia." (PMID 25999983, 2015). "The over-expression of GAS5 in prostate cancer cells reduces drug/UV resistance and promotes apoptosis." (PMID 26110379, 2015). "One famous example is the lincRNA GAS5; genetic aberrations at this lincRNA locus have been found in many types of tumors, including melanoma, breast, and prostate cancers." (PMID 24879036, 2014). "Interestingly, GAS5 overexpression was also observed in several other cancers, including colon, kidney, bladder, brain and prostate cancers." (PMID 40451925, 2025). "GAS5 is downregulated in prostate cancer cells compared with prostate epithelial cells." (PMID 35103065, 2022). "Here, we test the hypothesis that the expression of a lncRNA, grow arrest-specific 5 (GAS5) can be a biomarker for docetaxel response in castration resistant prostate cancer (CRPC) using both prostate cancer (PCa) cell lines and CRPC patient datasets." (PMID 34094978, 2021). "Moreover, this SNPs of GAS5 gene was reported significantly affecting the gleason score, disease stage and prognosis of prostate cancer." (PMID 31673232, 2019). "Furthermore, overexpression of GAS5 can significantly slow prostate cancer cell progression in vitro and tumor growth in vivo by inactivating the AKT signaling pathway." (PMID 28993733, 2017).
prostate carcinoma (continued). "GAS5, growth arrest-specific 5, was demonstrated to promote the apoptosis of prostate cancer cells." (PMID 26110379, 2015). "Notably, in an LNCaP xenograft model, GAS5 levels decline concomitant with the acquisition of castrate-resistance, which has important implications for the treatment of advanced prostate cancer." (PMID 26198250, 2015). "Finally, in prostate cancer cell lines, Pickard and colleagues reported a lncRNA transcribed from the growth arrest-specific 5 (GAS5) gene locus able to mediate apoptosis in UV-C irradiated 22RV1 or PC-3 cells." (PMID 24627686, 2014). "Additionally, lncRNA GAS5 has been proven to inhibit EMT in prostate cancer." (PMID 37229651, 2023). "However, few studies reported the expression levels of GAS5 in prostate cancer." (PMID 28771526, 2017). "A clinical study collected urine samples from 30 prostate cancer patients and 49 BPH patients to examine potential of lncRNAs GAS5 and lincRNA-p21 in prostate cancer diagnosis." (PMID 35773731, 2022). "Down-regulation of Growth arrest-specific 5 (GAS5) is correlated with enhanced cell proliferation and poorer prognosis of prostate cancer." (PMID 31673232, 2019). "lncRNA GAS5 was also found to enhance the therapeutic efficiency in various cancers, such as non-small cell lung cancer (NSCLC), pancreatic cancer, and prostate cancer, thereby acting as a valuable tumoral suppressor." (PMID 32967267, 2020). "In addition, GAS5 interacts with E2F1 and enhances the binding of E2F1 to the P27Kip1 promoter in prostate cancer." (PMID 30853980, 2019). "In a study of prostate cancer cell lines, mTOR inhibitors enhanced GAS5 transcript levels in androgen-sensitive but not in androgen-independent cell lines, which exhibit especially low levels of endogenous GAS5 lncRNA." (PMID 31533355, 2019). "The expression of GAS5 was identified to downregulate microRNA-21(miR-21)/miR-1284, then increase the expression PTEN/ PCDC4/AKT and result in cell apoptosis and limit proliferation of prostate cancer cell." (PMID 31673232, 2019). "Moreover, correlation analysis also revealed miR-940 is positively correlated with GAS5 (PCC=0.47) and ZFAS1 (PCC=0.49) which suggests miR-940 also likely to be involved in prostate cancer." (PMID 29416676, 2018). "GAS5 (Growth arrest-specific 5), located on chromosome 1q25.1, expressed a relatively low level of PC3, DU145, and LNCaP cells in comparison to RWPE-1 normal prostate cells and its reintroduction accelerates apoptosis in prostate cancer cell lines." (PMID 30037351, 2018). "The two SNPs (rs55829688 T > C and rs145204276 INS > DEL) in GAS5 have been shown to upregulate GAS5 expression by methylating its promoter, and then GAS5 binds miR-21 and miR‐2184 directly as a sponge, targeting PTEN, PDCD4, respectively, further inducing cell apoptosis in Prostate Cancer (PCa)." (PMID 35837102, 2022). "In addition, genetic aberrations at the GAS5 locus have been found in many types of tumors, including melanomas and breast and prostate cancers, though their functional significance has not yet been established." (PMID 23680400, 2013). "As expected, GAS5 transcript was abundant in HUVEC and normal breast epithelial cells (MCF10 cell line, data not shown), but barely detectable in all tested breast and prostate cancer cells." (PMID 27922078, 2016).
hepatocellular carcinoma (55 papers, 2015 to 2025). A malignant tumor that arises from hepatocytes. "In the liver tissues of mice with induced NAFLD, lncRNA GAS5 is elevated and linked to the development of hepatocellular carcinoma." (PMID 40868128, 2025). "LncRNA GAS5 (GAS5) is associated with hepatocellular carcinoma development and is upregulated in the liver tissues of HFD-induced NAFLD mice." (PMID 35322757, 2022). "The deletion allele of rs145204276 is significantly associated with an increased risk of hepatocellular carcinoma (HCC) and is positively correlated with higher levels of GAS5 in HCC tissue." (PMID 32354045, 2020). "For example, GAS5 acts as a tumor suppressor in hepatocellular carcinoma by inhibiting migration and invasion through modulating miR-21, while in cholangiocarcinoma, it has a promoting effect by regulating hsa-miR-1297." (PMID 39958058, 2025). "Additional findings support a tumor-promoting function of the aberrant GAS5/miR-21 axis via the PTEN/PIK3 or SPRY1/p21 pathways in hepatocellular carcinoma, oral squamous cell carcinoma, bladder cancer cells, and ovarian cancer." (PMID 39941145, 2025). "Similar to our findings, expression analysis revealed that GAS5 is downregulated in NK cells isolated from patients with hepatocellular carcinoma." (PMID 40781182, 2025). "In hepatocellular carcinoma, GAS5 has been found to enhance radiosensitivity via sponging miR-144-5p, which subsequently upregulates the expression of ATF2." (PMID 39958058, 2025). "In hepatocellular carcinoma, GAS5 attenuates cell viability and invasion by boosting p21 expression via binding YBX1." (PMID 37639158, 2023). "Concerning GAS5, several studies have reported that its expression is typically reduced in different cancer types, including hepatocellular carcinoma (HCC), head and neck squamous cell carcinoma, glioblastoma, bladder, and non-small cell lung cancer (NSCLC)." (PMID 37444428, 2023). "The novel TCPOBOP-inducible lncRNAs include lnc4278/Dancr, lnc14777/Snhg1, and lnc10895/Snhg10, which promote hepatocellular carcinoma through their actions as miRNA sponges, and lnc733/Gas5, which is also a miRNA sponge and acts to inhibit liver fibrosis." (PMID 33761883, 2021). "HBx-downregulated lncRNA GAS5 inhibits the cell viability and invasion of hepatocellular carcinoma cell lines by activating Y-box-binding protein 1/p21 (YBX1/p21) signaling." (PMID 34830378, 2021). "It has been suggested that the lncRNA GAS5 suppresses hepatocellular carcinoma cell migration and invasion as well as liver fibrosis." (PMID 32413995, 2020). "Hepatocarcinoma is one of the most common tumors in digestive system tumors, and GAS5 plays an important role in hepatic carcinoma." (PMID 30606744, 2019). "Overexpression of GAS5 downregulates the vimentin and upregulates the E-cadherin level in hepatocellular carcinoma cells." (PMID 30564069, 2018). "The GAS5 directly binds miR-21 to down-regulate its expression at exon 4 of GAS5 and negatively regulate the expression of miR-21 in hepatocellular carcinoma." (PMID 30534359, 2018). "GAS5 has been reported as a tumor suppressor and was down-regulated in lung, gastric and hepatocellular cancer." (PMID 28771526, 2017). "For example, lncRNA GAS5 has been shown to be significantly down-regulated in hepatocellular carcinoma tissues." (PMID 28938565, 2017). "In HCC, the overexpression of GAS5 significantly promoted the apoptosis of hepatoma cells by negatively regulating the vimentin expression, a well-defined intermediate filament that has been linked to a more aggressive status in this tumor." (PMID 28392501, 2017). "However, our comprehensive analyses revealed aberrant overexpression of GAS5 in various cancers, with a direct association with SMARCA4 in hepatocellular carcinoma (HCC)." (PMID 40451925, 2025).
hepatocellular carcinoma (continued). "All lncRNAs selected in this study have established roles in HCC pathogenesis, UCA1, GAS5, LINC00152, and LINC00853, were chosen based on their established functional relevance in hepatocellular carcinoma (HCC) and their demonstrated potential as diagnostic biomarkers." (PMID 39609501, 2024). "GAS5 expression was shown to be inconsistent in hepatocellular carcinoma." (PMID 35736636, 2022). "CYP2C8 can be regulated by GAS5/miR-382-3p in hepatocellular carcinoma and play an anticancer role." (PMID 35265613, 2022). "Likewise, downregulated GAS5 in hepatocellular cancer (HCC) cells resulted in decreased PTEN levels and increased doxorubicin resistance in HCC." (PMID 35736636, 2022). "Moreover, it has been reported that GAS5 inhibits NAFLD development to hepatocellular carcinoma by controlling the Kupffer cell M1/M2 polarization." (PMID 35322757, 2022). "GAS5 was shown to sensitize hepatocellular cancer cells to chemotherapy by sponging miR-222." (PMID 33076450, 2020). "In addition, as a ceRNA of miR‐21, lncRNA GAS5 can regulate the levels of miR‐21 expression in cells of hepatocellular carcinoma." (PMID 32860492, 2020). "Similarly, GAS5 directly acts as a sponge for miR-21, suppressing its expression and subsequently inhibiting hepatocellular carcinoma proliferation." (PMID 33076450, 2020). "Taken together, lncRNA GAS5 may act as the treatment target of CL in hepatocellular carcinoma; however, specific downstream gene of lncRNA GAS5 still needs further study." (PMID 31178721, 2019). "In vitro, overexpression of GAS5 can reduce Vim protein significantly, and GAS5 will increase the expression of E-cad, indicating that GAS5 regulates the proliferation and invasion of hepatoma cells by regulating Vim." (PMID 30606744, 2019). "Moreover, lncRNA GAS5 could promote tumor progression by targeting TP53INP1 in hepatocellular carcinoma and the GAS5/TP53INP1 axis was also identified as gain interaction in our LIHC DysCeNet." (PMID 34222227, 2021). "The low expression of GAS5 may reflect the poor survival rate of patients with hepatocellular carcinoma (HCC)." (PMID 35837102, 2022). "MiR-21 sponged by GAS5 has been reported in OSCC, hepatocellular carcinoma, laryngeal squamous cell carcinoma and ovarian cancer." (PMID 32661236, 2020). "GAS5 expression was also suggested to be an indicator of overall survival in CRC and hepatocellular carcinoma." (PMID 27391432, 2016).